GMPPA (GDP-mannose pyrophosphorylase A)
Description:
Regulatory subunit of the GMPPA-GMPPB mannose-1-phosphate guanylyltransferase complex; reduces the catalytic activity of GMPPB when part of the complex. Mediates allosteric feedback inhibition of GMPPB catalytic activity upon binding GDP-alpha-D-mannose. Together with GMPPB regulates GDP-alpha-D-mannose levels.
Synonyms: AAMR
Tractability: Small molecule: a structure with a bound ligand is known. PROTAC: ubiquitination databases record sites on it; its protein half-life has been measured.
Gene: Protein-coding gene on chromosome 2 (219,498,618 to 219,513,898, forward strand). Ensembl gene ENSG00000144591.
Subcellular location: Cytoplasm
Subcellular location (Human Protein Atlas): Nucleoplasm
Pathways (Reactome):
Metabolism of proteins: Synthesis of GDP-mannose
Gene Ontology:
Molecular function: enzyme binding; enzyme inhibitor activity; mannose-1-phosphate guanylyltransferase (GTP) activity; molecular sensor activity; protein binding; transferase activity
Biological process: GDP-mannose biosynthetic process
Cellular component: cytoplasm; extracellular exosome; GDP-mannose pyrophosphorylase complex; cytosol
Genetic constraint (gnomAD): Loss-of-function variants: 34 observed, 41.6 expected, observed/expected ratio (o/e) 0.82, 90% interval 0.62 to 1.09. The upper end of that interval is the gene's LOEUF score, 1.09, which puts it in group 4 of 6, group 1 being the genes least tolerant of losing a copy. Missense variants: 382 observed, 448.8 expected, observed/expected ratio (o/e) 0.85, 90% interval 0.78 to 0.93. Synonymous variants: 171 observed, 172.76 expected, observed/expected ratio (o/e) 0.99, 90% interval 0.87 to 1.12.
Gene-disease validity (ClinGen):
ClinGen rates the evidence that GMPPA causes each of these diseases.
alacrima, achalasia, and intellectual disability syndrome (autosomal recessive): Definitive.
Homologues: Orthologues: chimpanzee GMPPA (100% identical), macaque GMPPA (99% identical), mouse Gmppa (98% identical), rat Gmppa (97% identical), guinea pig GMPPA (96% identical), pig GMPPA (94% identical), dog GMPPA (90% identical), rabbit GMPPA (89% identical), tropical clawed frog gmppa (75% identical), zebrafish gmppaa (73% identical), zebrafish gmppab (72% identical), Drosophila melanogaster Gmppa (56% identical), and 1 more. Paralogues in human: GMPPB (33% identical), EIF2B5 (23% identical), EIF2B3 (17% identical).
Diseases named in the same sentence as GMPPA in open-access papers:
GMPPA is named in the same sentence as 13 diseases in open-access papers, as found by Europe PMC text mining. Sharing a sentence is not in itself a finding about the gene and the disease. The quoted sentences say what the papers report.
Achalasia (4 papers, 2022 to 2025). A disorder of esophageal motility characterized by the inability of the lower esophageal sphincter to relax during swallowing and by inadequate or lacking peristalsis in the lower half of the body of the esophagus. "Achalasia is identified in alacrima, achalasia, and mental retardation (AAMR) syndrome (OMIM#615510)—an autosomal recessive disease caused by loss-of-function variants in GMPPA." (PMID 40979943, 2025). "A syndrome of alacrima, achalasia, and mental retardation (OMIM: 615510) has been linked to biallelic variants in the guanosine diphosphate-mannose pyrophosphorylase A (GMPPA) gene." (PMID 39003500, 2024). "We recently showed that mutations in GDP-mannose pyrophosphorylase A (GMPPA) can cause a syndrome characterized by alacrima, achalasia, mental retardation, and myopathic alterations (AAMR syndrome)." (PMID 36672654, 2023). "We recently reported that mutations of its catalytically inactive homolog GDP-mannose-pyrophosphorylase-A (GMPPA) cause AAMR syndrome, a disorder characterized by achalasia, alacrima, mental retardation, and muscle weakness." (PMID 36672654, 2023). "We report a 9-month-old female born to nonconsanguineous parents with achalasia and alacrima found to have two novel compound heterozygous variants in the GMPPA gene associated with GMPPA-CDG." (PMID 35665995, 2022).
lung adenocarcinoma (3 papers, 2018 to 2021). A carcinoma that arises from the lung and is characterized by the presence of malignant glandular epithelial cells. "GMPPA (GDP-mannose pyrophosphorylase A) mutations were utilized for predicting lung adenocarcinoma, lung squamous cell carcinoma, and small cell lung cancer." (PMID 33996533, 2021). "Mutations in three genes (DNAJC2, GMPPA, or MMRN2) are negatively associated with survival in lung adenocarcinoma." (PMID 33791386, 2021). "Mutations in GMPPA, DNAJC2, and MMRN2 were significantly associated with patient mortality in lung adenocarcinoma of Pan-Lung Cancer cohort." (PMID 30419062, 2018).
liver cancer (1 paper, 2024). An epithelial or non-epithelial malignant neoplasm that arises from the liver. "After analyzing six tumor-specific signatures (IDI1, GMPPA, NME1, PSMB3, SPTLC1 and EBP), the gene effect and gene dependency were measured in different non-cancerous cell lines and liver cancer lines of human HCC." (PMID 38927057, 2024).
lung carcinoma (1 paper, 2018). "In LUAD of Pan-Lung Cancer cohort, mutations in DNAJC2, GMPPA, MMRN2, DRD3, and SETX were significantly associated with survival status, and those in DNAJC2, MMRN2, and SETX were significantly associated with overall survival." (PMID 30419062, 2018). "In LUAD of Pan-Lung Cancer cohort, mutations in GMPPA, DNAJC2, and MMRN2 showed significant negative associations with survival of patients while mutations in DRD3 and SETX showed significant positive association with survival." (PMID 30419062, 2018).
muscular dystrophies (1 paper, 2025). "In humans, mutations in GMPPA or GMPPB cause congenital disorders of glycosylation and muscular dystrophies." (PMID 40315235, 2025).
triple-A syndrome (1 paper, 2018). Triple A syndrome is a very rare multisystem disease characterized by adrenal insufficiency with isolated glucocorticoid deficiency, achalasia, alacrima, autonomic dysfunction and neurodegeneration. "Although patient 2 showed typical clinical symptoms of triple A syndrome, he did not carry a pathogenic AAAS or GMPPA mutation." (PMID 29334914, 2018).
tumor (2 papers, 2021 to 2024). "GMPPA, which is involved in glycolytic processes, has been implicated as a negative prognostic factor in several tumor types." (PMID 35004676, 2021). "In detail, the estimated IC50 levels of cisplatin were distinctly lower in low expression than in high expression of GSS, GMPPA, and OGDH, suggesting that these three genes could be used as biomarkers whose low expression indicates the tumor is more sensitive to cisplatin." (PMID 35004676, 2021).
GMPPA also shares sentences with these, for which no sentence is quoted: cancer (2 papers); lung squamous cell carcinoma (2); small cell lung carcinoma (2); depression (1); gastric cancer (1); infection (1).